MYCN (MYCN proto-oncogene, bHLH transcription factor)
Diseases named in the same sentence as MYCN in open-access papers (continued):
Sharing a sentence is not in itself a finding about the gene and the disease.
neuroblastoma (continued). "ID2 is a helix-loop-helix transcription factor controlled by MYC proteins that blocks differentiation and promotes cell proliferation, and MYB is a transcription factor that cooperates with MYCN in cell cycle regulation of MYCN-amplified neuroblastomas." (PMID 27242543, 2016). "This revealed a specific MYCN-signature described for MYCN-driven murine neuroblastomas also in the pancreatic tumors of LSL-MYCN;hGFAP-Cre mice." (PMID 27769070, 2016). "Nevertheless, the final output indicates that cinacalcet is mostly a pro-fibrotic stimulus in MYCN-amplified neuroblastomas." (PMID 26893368, 2016). "Recently, Puissant showed that bromodomain inhibition suppressed MYCN transcription in neuroblastoma." (PMID 26771642, 2016). "Neuroblastoma has several autochthonous or companion animal models, the most notable being MYCN- and ALK-expressing mice and zebrafish." (PMID 28035989, 2016). "To establish a time- and concentration-dependent biomarker response in a native neuroblastoma cell line we treated Kelly (MYCN-amplified, high MYCN protein) cells with NVP-BEZ235 for 1, 3, 6 and 12 h." (PMID 27438153, 2016). "Our study extends the previous findings to human neuroblastoma cells and shows the association of nuclear EYA1 with nuclear MYCN in both human neuroblastoma cell lines and primary neuroblastoma tumors." (PMID 28713571, 2016). "Suppression of SULF-2 using small interference RNA (siRNA) decreased cell proliferation in MYCN-amplified neuroblastoma cells, indicating that SULF-2 is a potential drug target." (PMID 26771642, 2016). "Concomitantly, genes that critically support neuroblastoma proliferation were down-regulated, such as MYCN, inhibitor of differentiation 2 (ID2) and MYB." (PMID 27242543, 2016). "Similar to the data with ABT-263, exogenous expression of MYCN markedly increased sensitivity to ABT-199 in MYCN-WT neuroblastoma cells and RPE-1 cells." (PMID 26859456, 2016). "The enhanced sensitivity of MYCN overexpressing neuroblastoma cell lines to PI3K/mTOR inhibition is somewhat surprising, since these cells lack intrinsic mutations in the PI3K pathway members PTEN or PIK3CA." (PMID 27438153, 2016). "Number of genes correlated with human achaete-scute homolog 1 (hASH1) and N-myc (MYCN) in human neuroblastoma." (PMID 28066180, 2016). "Next, we reported that the CaSR gene is silenced by genetic and epigenetic mechanisms in MYCN-amplified, unfavorable neuroblastomas." (PMID 26893368, 2016). "Neuroblastoma in adolescents and adults has been reported to lack MYCN oncogene amplification, which occurs in 20–30% of younger children." (PMID 27547479, 2016). "Taken together, CD9 is epigenetically and transcriptionally repressed by the chromatin-modifying enzyme, HDAC5, in association with MYCN, and CD9 expression can be triggered in neuroblastoma cells by inhibition of HDAC5." (PMID 27572323, 2016). "In summary, our results indicate that MYCN and differentiation-inducing miRNAs form a complicated interaction network in neuroblastoma cells, and we identified novel miRNA:MYCN inter-regulations that have not been identified previously." (PMID 27764804, 2016). "In this study, we took a pharmacogenomic approach to identify an effective combination-based targeted therapy for MYCN-amplified neuroblastoma." (PMID 26859456, 2016). "DFMO decreased RB phosphorylation in MYCN-amplified neuroblastoma cells and significantly decreased cell growth, likely mediated by the protein P27." (PMID 26771642, 2016). "Gene expression analysis identified MYCN as a novel AhR target gene repressed in neuroblastoma cells by a mechanism involving the transcription factor E2F1." (PMID 27243009, 2016). "Recently, a plethora of data has been generated regarding the oncogenic functions of MYCN in neuroblastoma." (PMID 27571165, 2016).
neuroblastoma (continued). "On the one hand, MYCN has been demonstrated to regulate expression of many miRNAs in the context of several cancer types including neuroblastoma." (PMID 27764804, 2016). "In diverse models of MYCN-amplified neuroblastoma, including a patient-derived xenograft model, this combination uniformly induced tumor shrinkage, and in multiple instances led to complete tumor regression." (PMID 26859456, 2016). "It is suggested that shedding of GD2 and MYCN amplification jointly characterize the most aggressive type of neuroblastomas." (PMID 27716771, 2016). "For example, amplifications of EGFR in gliomas, MYCN in neuroblastoma, MYC in acute myeloid leukemia, and ERBB2 in breast, ovarian, and lung cancers have been reported." (PMID 26755558, 2016). "MYCN-amplified neuroblastoma is particularly difficult to treat, attributed in part to the immunosuppressive tumor macrophage inhibition of DCs, NK cells, and T cells." (PMID 28536380, 2016). "We found that both concentrations of the Aurora A inhibitor MLN8237 (alisertib) and the Aurora A/B inhibitor VX680 (tozasertib) potently induced apoptosis in MYCN-amplified neuroblastomas when combined with ABT-199." (PMID 26859456, 2016). "Collectively, our data argue for a role of MYCN in the transcriptional repression of CD9 in neuroblastoma cells." (PMID 27572323, 2016). "This investigation also recapitulates a previous finding — miR-137 has been previously shown to be down-regulated by MYCN in neuroblastoma." (PMID 27764804, 2016). "In contrast, MYCN-WT neuroblastoma cell culture models and human xenografts proved insensitive to this combination." (PMID 26859456, 2016). "We show that nf1 deficiency in the fish leads to aberrant activation of RAS-MAPK signaling in MYCN-induced neuroblastoma, which promotes both tumor cell survival and proliferation, leading to marked acceleration of tumor onset and increased tumor penetrance." (PMID 27130733, 2016). "OTX015 is a BET bromodomain inhibitor which decreased cell proliferation in MYCN-amplified neuroblastoma cells in preclinical trials and is currently in Phase I clinical trials for other solid tumors." (PMID 26771642, 2016). "Consistent with the apoptosis data, the combination had a limited effect on MYCN-WT neuroblastoma cells and the RPE-1 cell line." (PMID 26859456, 2016). "NBLW and NBLW-R are paired cell lines originally derived from an infant with metastatic MYCN amplified Stage IVS (Evans Criteria) neuroblastoma, at diagnosis and relapse, respectively." (PMID 27888620, 2016). "Downregulation of SGO1 impaired proliferation and induced DNA damage followed by a senescence-like phenotype only in MYCN-overexpressing neuroblastoma cells." (PMID 27539729, 2016). "A Darwinian selection pattern was previously implied to explain the increased number of DMs that harbor MYCN in neuroblastoma cells." (PMID 27494853, 2016). "In our therapeutic approach, ABT-199 eliminates this pro-survival BCL-2 signal, thus allowing for MYCN-mediated pro-apoptotic signaling to help push the neuroblastoma cells toward the apoptotic threshold." (PMID 26859456, 2016). "Screening for enhancers of ABT-199 sensitivity in MYCN-amplified neuroblastomas, we demonstrate that the Aurora Kinase A inhibitor MLN8237 combines with ABT-199 to induce widespread apoptosis." (PMID 26859456, 2016). "MYCN amplification is detected in approximately 20% of neuroblastoma tumors, and amplification of greater than ten copies of MYCN is the strongest adverse prognostic indicator for this disease." (PMID 26771642, 2016). "We further examined combined MYCN knockdown and miR-506-3p overexpression in additional neuroblastoma cell lines." (PMID 27764804, 2016). "In this study we found that cisplatin-induced cytotoxic stress was able to stimulate BDNF production in the MYCN-amplified neuroblastoma cell line SK-N-BE by enhancing both transcription and translation of multiple BDNF mRNAs." (PMID 27256407, 2016).
neuroblastoma (continued). "Equivalent levels of MYCN expression were achieved in SHEP cells expressing wild-type MYCN (SHEP WT) in comparison to a range of established, tumor-derived neuroblastoma cell lines known to express high-levels of MYCN." (PMID 27438153, 2016). "This work provides a comprehensive view of MYCN regulations for exploring therapeutic targets in neuroblastoma, as well as insights into the mechanism of neuroblastoma tumorigenesis." (PMID 27167114, 2016). "The gene expressing ODC, ODC1, is activated by N-MYC and is upregulated in MYCN-amplified human neuroblastomas." (PMID 26771642, 2016). "In support of this, in vivo tissue targeted expression of ALKF1174L leads to the development of neuroblastoma in transgenic mice, and cooperates with MYCN to accelerate tumour onset with enhanced penetrance and lethality." (PMID 27888620, 2016). "Through integration of heterogeneous regulatory data, this study reveals the complexity of the role of MYCN as a driving oncogene for neuroblastoma." (PMID 27167114, 2016). "The number of genes identified using a two-fold cut-off following MYCN siRNA-mediated inhibition 30 h post-transfection, was similar to that found in a previous study in neuroblastoma using this time point." (PMID 27448979, 2016). "We confirmed these observations in two other MYCN-amplified neuroblastoma cell lines, IMR5 and SKN-Be2C, which showed similar patterns in sensitivity and biomarker modulation with all three drug treatments." (PMID 27438153, 2016). "In MYCN-overexpressing neuroblastoma cells, SGO1 knockdown induced DNA damage even in interphase, and this phenotype was independent of cohesin." (PMID 27539729, 2016). "Together, these results demonstrated higher sensitivity of MYCN amplified neuroblastoma cells to these agents as IC50s of all these inhibitors shifted upward in non-MYCN amplified cells." (PMID 26934655, 2016). "Altogether, this evidence supports the strong function of MYCN in controlling miR-137 expression in neuroblastoma." (PMID 27764804, 2016). "In order to investigate the molecular mechanisms responsible for etoposide chemoresistance, HTLA-230, a human MYCN-amplified neuroblastoma cell line, was chronically treated with etoposide at a concentration that in vitro mimics the clinically-used dose." (PMID 27683112, 2016). "We next sought to understand how the addition of MLN8237 further sensitized MYCN-amplified neuroblastoma cells to ABT-199." (PMID 26859456, 2016). "Using antisense oligonucleotides directed against human MYCN in MYCN-amplified human neuroblastoma cells yielded approximately half as much N-MYC protein expression compared to control and in vivo led to decreased tumor growth in transgenic MYCN mice." (PMID 26771642, 2016). "In particular, we have identified PRPS2 and SDC1 as genes that are positively regulated by both MYCN and TFAP4, and which represent novel candidate therapeutic targets for MYCN-driven neuroblastoma." (PMID 27448979, 2016). "For these experiments, we used the FDA-approved MEK inhibitor trametinib to treat primary neuroblastoma tumors that were growing in 3-week-old nf1a-/-;nf1b+/+;MYCN; EGFP fish." (PMID 27130733, 2016). "NVP-BEZ235, a potent inhibitor of both PI3K and mTOR-kinases, which is already in clinical trials for PI3K pathway-mutated adult cancers, eliminated intra-tumoral MYCN and induced regression of MYCN-driven transgenic neuroblastoma tumors in vivo." (PMID 27438153, 2016). "Similar results were demonstrated in MYCN-inducible SH-EP/TET21/N human neuroblastoma cells following tetracycline treatment." (PMID 27448979, 2016). "Together, these observations indicate that SGO1 is required for efficient progression through G2/M phase in MYCN-overexpressing neuroblastoma cells." (PMID 27539729, 2016). "We next used several different neuroblastoma cell and mouse models to investigate the nature of this relationship and the influence of MYCN on CD9 expression." (PMID 27572323, 2016).
neuroblastoma (continued). "MYB is a transcription factor that cooperates with MYCN in cell cycle regulation of MYCN-amplified neuroblastomas." (PMID 26893368, 2016). "In particular, neuroblastomas can occur when a protein called MYCN is over-produced and a tumor suppressor protein called NF1 is lost." (PMID 27130733, 2016). "In this study, we identify PRMT1 as a novel essential regulator of MYCN and its level as a significant independent prognostic marker in primary neuroblastoma tumors." (PMID 27571165, 2016). "siRNA-mediated suppression of TFAP4 in MYCN-expressing neuroblastoma cells led to inhibition of cell proliferation and migration." (PMID 27448979, 2016). "Our results highlight the potential of PRMT1 as a drug target for neuroblastoma and other cancers driven by the MYCN oncoprotein." (PMID 27571165, 2016). "Together, these data show a specific and potent in vitro efficacy of ABT-199/MLN8237 in MYCN-amplified neuroblastoma cells, even at relatively low concentrations of MLN8237." (PMID 26859456, 2016). "The use of DFMO in MYCN-amplified neuroblastoma cells has been demonstrated to deplete polyamines, impair proliferation, and induce G1 cell cycle arrest without apoptosis." (PMID 26771642, 2016). "show that MYCN-amplified neuroblastomas are sensitive to treatment with the BCL-2 inhibitor ABT-199 due to MYCN-driven increase of NOXA." (PMID 26859456, 2016). "MYCN, an oncogenic transcription factor of the Myc family, is a major driver of neuroblastoma tumorigenesis." (PMID 27167114, 2016). "Due to the difficulty in drugging MYCN directly, revealing the molecules in MYCN regulatory networks will help to identify effective therapeutic targets for neuroblastoma therapy." (PMID 27167114, 2016). "Wnt and retinoic acid co-treatments synergise, representing a promising combination treatment for MYCN-amplified neuroblastoma." (PMID 27531891, 2016). "Here, we have established MYCN-amplified neuroblastoma PDXs via injection of fresh tumor from a neuroblastoma patient into CB17 SCID mice for preclinical evaluation of this combination therapy." (PMID 26859456, 2016). "Ever since the identification of MYCN amplification in primary neuroblastoma, an oncogenic role of MYCN has been assumed." (PMID 27769070, 2016). "After 5 days of treatment, cells treated with the combination demonstrated marked growth inhibition in the MYCN-amplified neuroblastoma cells compared with MYCN-WT cells; the single agents had limited and variable effects across the MYCN-amplified cell lines." (PMID 26859456, 2016). "The NBLW cell line was established from the primary untreated (right) adrenal tumour of a 6 month old male patient with MYCN amplified Stage IVS (Evans Criteria) neuroblastoma with metastasis to the liver." (PMID 27888620, 2016). "Together, our data clearly implicate MYCN as a downstream mediator of ALK signaling in neuroblastoma." (PMID 27732954, 2016). "Using data from our large drug screen we predicted, and subsequently demonstrated, that MYCN-amplified neuroblastomas are sensitive to the BCL-2 inhibitor ABT-199." (PMID 26859456, 2016). "In neuroblastoma cells, treatment with siFAK led to decreased cell survival, with a larger effect in MYCN-amplified cell lines." (PMID 26771642, 2016). "Collectively, these data indicate that TFAP4 is a direct transcriptional target of MYCN in neuroblastoma." (PMID 27448979, 2016). "We therefore designed a chemical-genetic screen using isogenic (SHEP neuroblastoma) cells varying in expression of wild-type or CPD-mutated, stabilized MYCN, and we assessed selective sensitivity to treatment with a library of 228 drugs or chemical probes." (PMID 27438153, 2016). "MYCN regulates neuroblastoma cell differentiation, which is one of the mechanisms underlying its oncogenic function." (PMID 27764804, 2016). "The MYCN amplified neuroblastoma cell lines IMR-32 and SK-N-BE showed the lowest levels of active β-catenin." (PMID 27036398, 2016).
neuroblastoma (continued). "This is consistent with our previous report in nf1 wild-type fish that MYCN-induced neuroblastoma tumors arise from adrenal sympathetic neuroblasts that are prevented from differentiation into chromaffin cells by the overexpression of MYCN." (PMID 27130733, 2016). "MycN regulates the expression of these polycomb genes and contributes to the pathogenesis of neuroblastoma." (PMID 26815535, 2016). "The etiology of neuroblastoma is heterogeneous and includes amplification of the MYCN or anaplastic lymphoma kinase oncogenes and the allelic loss of chromosomes 1p, 3p, or 11q." (PMID 27824082, 2016). "The positive relationship between PMAIP1 mRNA expression and MYCN mRNA expression was also observed in a large collection of neuroblastoma cell lines and confirmed in our neuroblastoma cell line panel." (PMID 26859456, 2016). "Amplification of MYCN is the driving oncogenic event in a subset of the most aggressive neuroblastomas; exposure to MYCN antisense oligonucleotides results in tumor growth inhibition." (PMID 26859456, 2016). "The induction of apoptosis in MYCN-amplified neuroblastoma cells was mitigated by BIM siRNA, implicating that the disruption of BIM/MCL-1 complexes leads to loss of MCL-1-bound BIM and contributes to ABT-199/MLN8237-mediated apoptosis." (PMID 26859456, 2016). "The protein sulfatase 2 (SULF-2) is overexpressed in MYCN-amplified neuroblastoma cells but expressed at a much lower level in MYCN-unamplified cells." (PMID 26771642, 2016). "Although useful, Urbani's model was not representative of the more aggressive and therapy-refractory forms of neuroblastoma, characterized by the amplification of the MYCN proto-oncogene." (PMID 27683112, 2016). "For example, MYCN is well-studied biomarker for neuroblastoma and inactivation of it results in impaired cell growth and enhanced cell death in neuroblastoma." (PMID 27769251, 2016). "Since MYCN gene amplification occurs in about 50% of high-risk neuroblastoma patients, we used three MYCN-amplified and three non-MYCN-amplified neuroblastoma cell lines in present study." (PMID 26934655, 2016). "MLN 8237, which promotes MYCN degradation by AuroraA functions, prolongs the survival of mice in the TH-MYCN model of neuroblastoma and repressed cell viability of neuroblastoma cells in vitro." (PMID 27769070, 2016). "Lastly, we noted that this combination was effective at even low concentrations of MLN8237 (10 nM MLN8237) in the MYCN-amplified neuroblastoma cells." (PMID 26859456, 2016). "The first genetic alteration to be described in neuroblastoma was the amplification of the oncogene MYCN." (PMID 27242543, 2016). "Patient 003 received carboplatin, etoposide and vincristine for the treatment of stage 4S neuroblastoma with MYCN amplification, at a gestational age of 40 weeks (BW 2.5 kg)." (PMID 26875154, 2016). "In neuroblastoma, MYCN, LIN28B and let-7 seem to be involved and MYCN amplification is correlated with adverse clinical outcome." (PMID 26858029, 2016). "The benefit of MYCN reduction by MLN8237 outweighs any relief of a pro-apoptotic signal, consistent with the anti-cancerous effects of targeting MYCN alone in MYCN-amplified neuroblastoma." (PMID 26859456, 2016). "Complementarily, in a very recent approach, CASP8 302His was associated with worse overall and event-free survival in patients with MYCN-amplified neuroblastoma tumors." (PMID 27507139, 2016). "Second, due to high BCL-2/BCL-xL ratios in these cancers, MYCN-amplified neuroblastoma cells retain sensitivity to the BCL-2 inhibitor ABT-199." (PMID 26859456, 2016). "We show that PI3K/mTOR inhibitors selectively killed MYCN-expressing neuroblastoma tumor cells, and induced significant apoptosis of transgenic MYCN-driven neuroblastoma tumors concomitant with elimination of MYCN protein in vivo." (PMID 27438153, 2016).